NMB (neuromedin B)
Diseases named in the same sentence as NMB in open-access papers (continued):
Sharing a sentence is not in itself a finding about the gene and the disease.
heart failure (1 paper, 2021). Inability of the heart to pump blood at an adequate rate to meet tissue metabolic requirements. "For the differential genes associated LMNA alone with euchromatin, we obtained 5 candidate genes (EGR2, NMB, CREBBP, PRF1, and TENM4), of which EGR2 and NMB have been reported to involve in myocardial ischemia and heart failure, respectively." (PMID 33407844, 2021).
medulloblastoma (1 paper, 2021). A malignant, invasive embryonal neoplasm arising from the cerebellum. "A later study of the medulloblastoma cell lines DAOY and D283 reported both cell lines expressed NMBR mRNA and NMB mRNA." (PMID 34539578, 2021). "In contrast to the growth inhibitory effect of higher concentrations of cetuximab in the medulloblastoma cell line DAOY, neither the addition of NMB nor the NMBR antagonist BIM-23127 had an effect on the cell line’s growth or viability when present alone." (PMID 34539578, 2021).
melanoma (1 paper, 2009). A malignant, usually aggressive tumor composed of atypical, neoplastic melanocytes. "A humanized toxin-conjugated NMB antibody was shown to be effective in killing antigen-positive melanoma, suggesting that this therapeutic may have potential in the treatment of other NMB positive malignancies." (PMID 19146682, 2009).
migraine (1 paper, 2022). "Neuropeptides directly associated with pain or migraine from significantly differentially expressed neuropeptide prohormone genes include apelin (APLN), cortistatin (CORT), IGF2, neuromedin B (NMB), neuropeptide W (NPW), PDGFA and platelet-derived growth factor, D polypeptide (PDGFD), TAC4, and VIP." (PMID 35453627, 2022).
neuroendocrine tumors (1 paper, 2011). "The preliminary results give evidence for a higher BZH3 uptake, which is related to higher bombesin and neuromedin B gene expression than that of ανβ3 in neuroendocrine tumors." (PMID 22214362, 2011).
osteoarthritis (1 paper, 2021). A noninflammatory degenerative joint disease occurring chiefly in older persons, characterized by degeneration of the articular cartilage, hypertrophy of bone at the margins and changes in the synovial membrane. "We then determined whether NMB expression was differentially regulated in MSC samples from osteoarthritis (OA) patients, for which chondrogenesis is known to be impaired." (PMID 34663442, 2021).
rectal cancer (1 paper, 2025). A primary or metastatic malignant neoplasm that affects the rectum. "Following adjustment for tumor purity, we identified distinct immune marker profiles correlated with NMB expression in colon and rectal cancers." (PMID 40486508, 2025).
sarcopenia (1 paper, 2024). Progressive decline in muscle mass due to aging which results in decreased functional capacity of muscles. "Consistently across the three outcomes, RXRA, MDM1, RBL2, KCNJ2, and ADHFE1 were identified as risk factors, while NMB, TECPR2, MGAT3, ECHDC2, and GINM1 were identified as protective factors, all with potential as biomarkers for sarcopenia progression." (PMID 39409102, 2024).
triple-negative breast carcinoma (1 paper, 2022). An invasive breast carcinoma which is negative for expression of estrogen receptor (ER), progesterone receptor (PR), and human epidermal growth factor receptor 2 (HER2). "In the case of triple-negative breast cancer, numerous targets have been evaluated, including Trop-2 receptors, zinc transporter LIV-1, PTK-7, NMB glycoproteins, and ephrin receptors." (PMID 35267507, 2022).
tumor (17 papers, 2010 to 2025). "Correlation studies identified significant associations between NMB expression levels and key clinicopathological parameters, including tumor differentiation, T stage, N stage, and recurrence status." (PMID 40486508, 2025). "Correlation studies with clinicopathological parameters demonstrated that NMB expression levels were significantly associated with tumor differentiation grade, T and N classification, and recurrence status." (PMID 40486508, 2025). "ELISA showed a significant decrease in NMB concentration in the cell supernatant of RSC96 cells / DRG co-cultured with these NMB-deficient tumor cells." (PMID 39214988, 2024). "Thus, the heterogeneity of NMB expression in tumor tissues may be caused by the heterogeneity of hormone expression." (PMID 39214988, 2024). "Functional characterization of NMB's tumor-regulatory capacity was conducted through colony formation assays, MTT proliferation tests, wound healing experiments, and transwell migration/invasion assays." (PMID 40486508, 2025). "Quantitative assessment using qRT-PCR demonstrated increased NMB RNA levels in tumor tissues, while ELISA quantification detected higher NMB concentrations in patient serum samples." (PMID 40486508, 2025). "In contrast, upregulated neuropeptides GAST and NMB correlated negatively with upregulated ICGs (p < 0.05), which is indicative of their potential role in anti-tumor immunomodulation." (PMID 40805163, 2025). "Immunohistochemical examination of tissue microarrays from 61 CRC cases showed predominant cytoplasmic localization of NMB protein, with significantly higher positive staining rates in tumor tissues versus normal controls (p < 0.001)." (PMID 40486508, 2025). "Functional assays demonstrated that the NF-κ B activator TNF-α effectively counteracted the inhibitory effects of NMB silencing on tumor cell proliferation, migration, and invasion." (PMID 40486508, 2025). "qRT-PCR analysis demonstrated significant upregulation of NMB mRNA in tumor tissues relative to matched paracancerous controls." (PMID 40486508, 2025). "Initial examination of TCGA data revealed significantly elevated NMB mRNA levels in tumor tissues compared to both normal controls (p < 0.001) and paired para-cancerous tissues (p < 0.001)." (PMID 40486508, 2025). "NMB has been reported to promote the growth, differentiation and invasion of these tumor cells in an autocrine manner." (PMID 39214988, 2024). "Our preliminary findings suggest that estrogen, l-glutamic acid, triiodothyronine (T3), and γ-GABA can upregulate NMB mRNA in tumor cells." (PMID 39214988, 2024). "Our results revealed higher expression of the CD276 and NMB proteins in tumor than in normal tissues, whereas CBX6 was only highly expressed in normal intestinal mucosal tissues." (PMID 37428291, 2023). "Glembatumumab vedotin mAb is conjugated to the cytotoxic drug monomethyl auristatin E. This mAb targets glycoprotein NMB, expressed on the surface of tumor cells, releasing the drug and inducing tumor cell death." (PMID 28970830, 2017). "NMB plays an important role in stimulating tumor growth and tumor angiogenesis through its cognate receptor, NMB-R." (PMID 24349381, 2013). "NMB is also aberrantly expressed by a variety of cancers and is involved in tumor cell proliferation." (PMID 21060863, 2010). "Functional validation experiments utilizing TNF-α, a potent NF-κ B pathway activator, demonstrated that pathway stimulation could effectively rescue the suppression of tumor cell proliferation, migration, and invasion induced by NMB knockdown." (PMID 40486508, 2025). "NMB secreted from tumor cells induced Schwann cell activation and axonal extension, which could be blocked by the selective NMBR antagonist PD168368." (PMID 39214988, 2024). "This gene encodes the transmembrane glycoprotein NMB (non-metastatic melanoma protein B), which was initially described as a regulator of tumor growth." (PMID 37047799, 2023).
tumor (continued). "Other upregulated genes included NR3C1, NMB, and COTL1, which are coordinately expressed with PDCD1, CXCL13, and ENTPD1 by tumor infiltrating CD4+ T cells." (PMID 40956619, 2025). "Molecular investigations uncovered that NMB protein stability is regulated through USP21-dependent deubiquitination, leading to subsequent activation of the NF-κB signaling cascade and tumor progression." (PMID 40486508, 2025). "Tissue microarray analysis of paired tumor and normal tissues from 61 CRC patients revealed significantly elevated NMB expression through immunohistochemical staining." (PMID 40486508, 2025). "The strong correlations between neuropeptides PTHLH, NMB, APLN, and GAST with these neurotrophic factors suggest a coordinated mechanism through which tumor cells recruit and sustain neuronal infiltration." (PMID 40805163, 2025). "Bombesin-like peptides, including NMB and gastrin-releasing peptide (GRP), are released by malignant tumor cells and act as autocrine growth factors and mitogens that influence proliferation and cell cycle progression." (PMID 24349381, 2013). "Upregulated neuropeptide genes, such as PTHLH, Gastrin (GAST), Secretogranin V (SCG5), Neuromedin B (NMB), and Apelin (APLN), were positively correlated with upregulated neurotrophic factors, which were consistent with their roles in tumor progression and neuroimmune crosstalk." (PMID 40805163, 2025). "Some peptidergic genes such as CALCA and GRP that are expressed in almost all normal PNECs were expressed in few if any tumor cells, whereas NPW, NMB, and CARTPT that are expressed in only rare PNECs were expressed in most (NPW) or many (NMB, CARTPT) of the tumor cells." (PMID 36469459, 2022). "NMB is expressed in non-tumorigenic cells, but its expression is low to undetectable in malignant cells, and several studies have shown that NMB may act as a tumor suppressor." (PMID 35203526, 2022).
cancer (9 papers, 2010 to 2025). A tumor composed of atypical neoplastic, often pleomorphic cells that invade other tissues. "For instance, a study has shown that the macrophage-derived soluble glycoprotein NMB (GPNMB) induces cancer stemness and metastasis via CD44 and IL-33." (PMID 41174767, 2025). "Accumulating evidence reveals that NMB acts through the NMB-R to promote the proliferation of various types of normal and cancer cells through activation of ERK1/2 signaling." (PMID 24349381, 2013). "The glycoprotein NMB, or GPNMB, has been shown to be overly expressed in several human cancers, including NSCLC." (PMID 36359256, 2022). "Cancer cells produce and secrete the neuropeptides CCK/gastrin, GRP and NMB, bradykinin, and vasopressin." (PMID 29262666, 2017). "Interestingly, also other members of the neuromedin family of neuropeptides, such as neuromedin B (NMB) and gastrin releasing peptide (GRP), have been identified as cancer-promoting factors in human tumors." (PMID 28423716, 2017).
infection (3 papers, 2018 to 2021). The state of being infected such as from the introduction of a foreign agent such as serum, vaccine, antigenic substance or organism. "The gene csf2 was significantly upregulated after infection with the NmB wild type strain as well as during the infection with the NmB capsule-deficient mutant when Erk1/2 signalling was inhibited." (PMID 34863201, 2021). "A microarray-based transcriptome analysis of HIBCPP cell infection with wild type and capsule-deficient mutant NmB hinted towards an NFκB-mediated pro-inflammatory immune response that involved up-regulation of the transcription factor IκBζ." (PMID 34863201, 2021). "The inhibition of the p38 signalling pathway significantly reduced infection rates only for the NmC capsule-deficient mutant, while the number of intracellular bacteria remained unchanged for the NmB capsule-deficient strain." (PMID 34863201, 2021). "In HBMEC, an in vitro cell culture system of the BBB, activation of MAPK p38 and JNK after infection with the NmB wild type strain MC58 and its capsule-deficient mutant has already been described." (PMID 34863201, 2021). "Taken together, these data suggest that the expression of NMB could reduce the susceptibility of mice to PR8 infection." (PMID 31601264, 2019). "Interestingly, Erk1/2 inhibition caused an increased infection by the capsule-deficient NmB mutant." (PMID 34863201, 2021). "The MACE analysis identified several genes that were regulated after infection with NmB specifically in the absence or presence of the inhibitor U0126." (PMID 34863201, 2021). "The induction of the expression of TCIM and RND1 was also previously determined after infection of HIBCPP cells with NmB." (PMID 34863201, 2021). "After infection of HIBCPP cells with the NmB strains, expression of nfκbia displayed similar fold-changes for both wild type strain and capsule-deficient mutant, while nfκbiz displayed a stronger upregulation after infection with the wild type strain." (PMID 34863201, 2021). "The inhibition of the Erk1/2 signalling during infection of HIBCPP cells resulted in a significant reduction of the intracellular bacteria of the NmB and NmC wild type strains." (PMID 34863201, 2021). "il8 also displayed a higher upregulation by NmB after infection of pre-treated cells than after infection of untreated HIBCPP cells." (PMID 34863201, 2021). "NmB isolates are grown in liquid culture suspension (rather than agar medium) to better mimic the conditions in the blood during infection." (PMID 29535195, 2018). "Furthermore, when synthetic NMBRA was injected into mice after PR8 infection, the cytokine expression profiles reversed relative to those under NMB treatment, thus corroborating the observed antiviral activity of NMB." (PMID 31601264, 2019). "Interestingly, whereas NmB and NmC wild type strains required active Erk1/2 and p38 pathways for infection, invasion by capsule-deficient mutants was independent of Erk1/2 and, in case of the NmB strain, of p38 activity." (PMID 34863201, 2021). "Interestingly, after Erk1/2 inhibition and infection of HIBCPP cells with the NmB strains, GO termini indicating an involvement of the NF-κB signalling pathway, a function of IL6, and a role of the tumour necrosis factor, were underrepresented compared to the untreated cells." (PMID 34863201, 2021). "Similar profiles of both NMB and NMBR expression following infection with PR8 were also observed in A549 cells." (PMID 31601264, 2019). "An exception is il17c, which is upregulated 22-fold after infection with the NmB wild type strain in absence of U0126, but is upregulated 79-fold by the bacteria when the Erk1/2 signalling pathway is inhibited." (PMID 34863201, 2021).
infection (continued). "However, a significant reduction in the number of intracellular bacteria of the NmC capsule-deficient mutant in HIBCPP cells could be observed, but no significant change in the infection rates for the NmB capsule-deficient mutant could be determined after inhibition of p38 signalling." (PMID 34863201, 2021). "When comparing the DEG of HIBCPP cells after infection with the NmB wild-type strain in presence and absence of the Erk1/2 inhibitor U0126, the determined fold changes are almost identical." (PMID 34863201, 2021). "Similarly to above, it was observed that the expression of NMB and NMBR increased in lung tissues following infection with PR8." (PMID 31601264, 2019). "Furthermore, the NMB/NMBR system appeared to increase IFN-α expression and decrease IL-6 expression after PR8 infection, which may serve to establish an antiviral state in the host." (PMID 31601264, 2019).
bacterial infections (1 paper, 2025). "Supplementation of growth media with this compound reduced lipooligosaccharide (LOS) sialylation of living N. meningitidis, thus providing an interesting starting point for the development of specific NmB CSS inhibitors as an alternative treatment strategy to fight bacterial infections." (PMID 41302389, 2025).
NMB also shares sentences with these, for which no sentence is quoted: Alzheimer disease (4 papers); amyotrophic lateral sclerosis (2); bipolar disorder (2); depression (2); eosinophilia (2); lung carcinoma (2); prostate carcinoma (2); Anxiety (1); attention deficit-hyperactivity disorder (1); autism spectrum disorder (1); bacterial meningitis (1); carcinoid (1); cervical intraepithelial neoplasia (1); Cognitive impairment (1); dry eye (1); generalized anxiety disorder (1); glioblastoma (1); head and neck squamous cell carcinoma (1); inflammation (1); Insulin resistance (1); lymph node metastasis (1); metabolic disease (1); myocardial ischemia (1); nervous system disease (1); obsessive-compulsive disorder (1); pancreatic cancer (1); Parkinson disease (1); prostate tumour (1); retina degeneration (1); Retinal dystrophy (1).
A further 5 diseases each share a sentence with NMB in 1 paper.